CD4 (CD4 molecule)
Diseases named in the same sentence as CD4 in open-access papers (continued):
Sharing a sentence is not in itself a finding about the gene and the disease.
co-infection (continued). "In the current study, we adjusted the effect to the baseline HIV viral load level, ART adherence status, HBV coinfection, and CD4 T cell count level." (PMID 36457041, 2022). "There is also evidence that Mtb-specific CD4+ T cells play a role in increased disease in Mtb-HIV coinfection." (PMID 36405707, 2022). "Depletion of CD4+T cells is believed to drive the progression of TB among patients with HIV coinfection." (PMID 35363160, 2022). "In the present study of 277 HIV-infected Chinese Yi ethnicity patients evaluated after a mean ART of 3.77 ± 1.21 years, we observed that a low baseline CD4 + cell count and HIV/HCV coinfection are associated with immune recovery in HIV patients." (PMID 35135485, 2022). "Although CD4+ T cells were significantly reduced in TB/HIV co-infection (P = 0.007), CD8+ T cells were significantly reduced in HIV-negative TB tissues (P = 0.04)." (PMID 35092727, 2022). "Another limitation in our study resides in the lack of data about the co-existence and the effect of other life-long viral coinfections, such as cytomegalovirus and Epstein–Barr on CD4+ and CD8+ T-cell count dynamics in our cohort of individuals during ART." (PMID 36366413, 2022). "A 25-year-old male with a history of intravenous drug abuse and a normal CD4 count developed CVT as the presenting manifestation of HIV-HBV co-infection." (PMID 36382206, 2022). "Male and female patients were compared in terms of age, CD4 cell count, HIV-1 RNA viral load, and HBV and HCV co-infections to determine association between groups." (PMID 36417469, 2022). "This is due to the known fact that HIV coinfection affected the integrity and function of CD4+ cells, which reduced the level of immunity and increased the risk of mortality." (PMID 36591001, 2022). "Anaemia was associated with the features suggestive of severe TB disease: high bacillary load, night sweats, low BMI, longer duration of fever, hyperthermia, HIV co-infection, low T-cell counts and low CD4:CD8 ratio." (PMID 35022106, 2022). "Anaemia was associated with night sweats, a longer duration of fever, low body mass index (BMI), hyperthermia, high sputum bacillary loads, HIV co-infection, and low CD4 and CD8 counts at bivariate analysis." (PMID 35022106, 2022). "HIV patients with CD4 count less than 350 cells/mm3 are 13.84 times more likely to have HIV-HBV-HCV co-infection as compared to those with CD4 count ≥350 cells/mm3 (OR 13.84, 95% CI: 2.90,66.10)." (PMID 35239716, 2022). "In this regard, a recent report evaluating T-cell and monocyte activation over the course of HCV direct-acting antiviral (DAA) therapy in HCV/HIV coinfection showed that after therapy CD4 T-cell activation positively correlated with monocyte activation." (PMID 35113890, 2022). "This study was conducted with an objective to analyze prevalence and risk factors associated with co-infection of hepatitis B virus (HBV) and hepatitis C virus (HCV) in HIV-positive patients with reference to their CD4+ T cell status." (PMID 35239716, 2022). "In our cohort, the prevalence of C. cayetanensis co-infection was higher among PLWH with CD4+ T cell counts below 200 cells/μL." (PMID 35889126, 2022). "Out of 241 patients with co-infection, 86.7% were from Brazil, 47.5% had <200 CD4+ T cells/μL and median viral load was 17,000 copies/μL." (PMID 34591866, 2021). "Study conducted in Kisumu district hospital found that the mean CD4 cell count for patients with co-infection was lower, (120 (+/-112) cells/mm3) than for patients with HBV mono-infection, 694 (+/-140) cells/mm3 which is in agreement with our current study." (PMID 33889269, 2021). "Few studies in Kenya have been done on HIV/HBV co-infection in relation to CD4 count and viral load." (PMID 33889269, 2021). "The results of the present study confirm that certain groups of people such as older, men, people who inject drugs, people with unsafe sex and TB co-infection had lower initial CD4 counts." (PMID 33766121, 2021).
co-infection (continued). "Of the outpatients with coinfection, the median CD4 count was 121 cells/mm3 (IQR = 36–184), and 2/20 had an undetectable viral load." (PMID 34943771, 2021). "Several factors including drinking alcohol, smoking tobacco, having mental illness, being bed ridden or ambulatory functional status, low CD4 count, and TB co-infection predicted LTFU." (PMID 33743815, 2021). "Overall, these data show that HIV coinfection leads to persistent skewing of CD4/CD8 ratio in the lung and a deficit in lung T cell functionality, most notably in IL-2 and IL-17 production." (PMID 33848273, 2021). "We found that factors including the ratio of the actual values to the cut-off values of AIGAs, WBC, N, HGB, CD4+T cells, IgG, IgM, IgA, serum globulin, ESR, and CRP were taken as potential risk factors for TM and NTM co-infection." (PMID 34376749, 2021). "TGF-β production by CD4+CCR5+ T cells was also higher in HIV/HCV coinfection, compared with HCV monoinfection and healthy controls (p = 0.004 and 0.001, respectively)." (PMID 34696504, 2021). "Coinfection increased the percentage of CD4+, CD4+IL4+ and CD8+IL4+ cells and decreased TNF-α secretion after BCG stimulation in the spleen when compared with the BCG infection alone." (PMID 33936040, 2021). "This study showed major features on T. cruzi-HIV co-infection and highlighted the prognostic role of CD4+ cells for reactivation and mortality." (PMID 34591866, 2021). "Factors including the ratio of the actual values to the cut-off values of AIGAs, WBC, N, HGB, CD4+T cells, IgG, IgM, IgA, serum globulin, ESR, and CRP were taken as potential risk factors for TM and NTM co-infection." (PMID 34376749, 2021). "In the present study, the AIGA titers and positive rates of patients with co-infection were significantly higher than those of other groups, while their CD4+T and CD3+T cell levels were significantly lower than those of other groups." (PMID 34376749, 2021). "Univariate analysis for risk factors of TM and NTM co-infection found that high level of AIGAs, WBC, N, HGB, IgG, IgM, IgA, serum globulin, ESR, and CRP and low level of CD4+T cells were taken as potential risk factors for TM and NTM co-infection." (PMID 34376749, 2021). "Results in the bivariate analysis showed that the variable residence, WHO clinical stage, education status, marital status, CD4 counts and weight were associated with TB/HIV co-infection." (PMID 35222561, 2021). "pylori co-infection had significantly higher CD4+ T cell counts and more often had undetectable HIV viremia, due to successful anti-retroviral therapy (ART)." (PMID 33690620, 2021). "TB co-infection, HBV co-infection, low CD4+ count at baseline and WHO clinical stages III/IV were associated factors for immunological discordant responses." (PMID 34118891, 2021). "Rapid progression was correlated with herpes simplex-2 virus coinfection, depression, low CD4+ T cell counts, and high set point viral load in acute infection stage." (PMID 34367176, 2021). "Coinfection risk factors also vary on epidemiological subjects such as age, marital status, sex, geographical location, HIV viral load, and CD4+ T cell count." (PMID 35222296, 2021). "In this analysis, younger age, a higher CD4 count, female sex, a lower level of education, and HCV co-infection were independently associated with a higher chance of achieving the outcome." (PMID 33953250, 2021). "Patients who died had lower CD4+ cells/μL counts and higher frequency of CD4+ count <200/μL at the co-infection diagnosis and at the reactivation time." (PMID 34591866, 2021). "The CD cardiac and indeterminate forms were the most prevalent, with the median CD4+ at co-infection diagnosis of 217 cells/μL and median viral load at co-infection diagnosis of 17,000 viral copies/μL." (PMID 34591866, 2021).
co-infection (continued). "HIV-1/HPgV-1 co-infection studies revealed lower CD4 T cell counts in individuals infected with HPgV-1 genotype 2a than genotype 2b and higher HPgV-1 viral loads in individuals with genotype 1 compared to genotypes 2a and 2b." (PMID 33499880, 2021). "There was a moderate Spearman correlation between CD4+ count at co-infection and reactivation diagnoses (r = 0.48)." (PMID 34591866, 2021). "Males, low baseline CD4+ count, poor/fair treatment adherence, and TB and HBV co-infections were significantly associated with higher immuno-virological discordance." (PMID 34118891, 2021). "TB co-infection, HBV co-infection and CD4+ count below 100 cells/μl at baseline were factors associated with immunological discordant responses." (PMID 34118891, 2021). "The findings acquired herein are similar to the reports above, indicating that the CD3+, CD4+ and CD4+/CD8+T cell levels change in HBeAg+ patients with HBV/TP co-infection." (PMID 34912410, 2021). "This study emphasizes the prognostic role of CD4+ cells on reactivation and mortality and the need of epidemiological surveillance for co-infection and CDR." (PMID 34591866, 2021). "We emphasize the role of higher CD4+ counts at the time of co-infection diagnosis as a protective factor for both reactivation and mortality, confirmed by multivariate logistic regression analyses." (PMID 34591866, 2021). "Characteristics associated with incident anemia included older age, female sex, black race/ethnicity, HCV coinfection, lower CD4 cell count, higher viral load, and lower eGFR, indicative of poor kidney function." (PMID 32197585, 2020). "To evaluate the role of HCV co-infection on immune parameters of HIV pathogenesis we compared the phenotypic profile of both CD4 and CD8 T-cells between HIV monoinfected and HIV/HCV coinfected patients before HCV eradication with the new DAAs-based therapy." (PMID 32942736, 2020). "Men continued to present with lower CD4 cell counts and have a larger proportion of TB co‐infection, which seems to be increasing over time." (PMID 32589367, 2020). "All 40 participants in study 2 had TB and HIV coinfection and had CD4 counts of 200 cells/mm3 or below." (PMID 31964788, 2020). "Among PLWH, those with mono-infection had a median CD4 of 394 cells/mm3 versus those with HIV/HCV coinfection whose mean CD4 cell count was lower at 364 cells/mm3, but both groups had a median baseline HIV viral load of 75 copies/mL." (PMID 33127959, 2020). "On multivariable logistic regression, factors associated with adherence to clinic appointments were 'alcohol consumption, age group, employment, baseline CD4 count, months on treatment and months on treatment by co-infection'." (PMID 33425151, 2020). "HIV-co-infection decreases the total number of CD4+ T cells since the virus preferentially replicates with in activated CD4+ T cells and macrophages, resulting in the disruption of granuloma to contain M. tuberculosis." (PMID 32033581, 2020). "Cytopenia was associated with femaleness, a lower BMI, a lower CD4+ T-cell count, a higher viral load, WHO stage IV, and coinfection with HBV." (PMID 32090076, 2020). "In conclusion, in HIV-infected patients, HCV co-infection, older age, alcohol abuse and CD4/CD8 ratio alone or in combination, seem to correlate with fibrogenesis in the liver." (PMID 32252653, 2020). "There were several nucleotides and amino acids with distinct distributions across the three study groups, although no obvious clustering of NS5B sequences was observed based on HIV co-infection or CD4 cell count." (PMID 32750098, 2020). "HIV co-infection was identified in 20 (83%) participants, with a median CD4 count of 35 cells per μL (IQR 17–74); four (20%) patients with HIV co-infection were receiving antiretroviral therapy at enrolment." (PMID 32085847, 2020). "In contrast to this, four out of five participants with Enterovirus A strain co-infection had CD4+ T cell counts below 200 cells/μL." (PMID 32079128, 2020).
co-infection (continued). "In our cohort of HIV-infected individuals HCV/HIV co-infection, older age, alcohol abuse and CD4/CD8 ratio seem to correlate with fibrogenesis in the liver." (PMID 32252653, 2020). "HIV-coinfection was found in 62.9% (39/62), with a CD4 count of below 200 helper cells/μl in almost half (46.2%, 18/39) of HIV-positive patients." (PMID 32381002, 2020). "SIV co-infection and CD4 depletion also changed the overall composition of T cells within lung granulomas that produce these cytokines and granzyme B." (PMID 32730321, 2020). "Risk factors for cytopenia in HAART-naïve patients were a CD4 cell count<200 cells/μL, femaleness, WHO stage IV, coinfection with hepatitis B virus (HBV), BMI <18.5 kg/m2, a viral load ≥100,000 copies/ml, and age ≥40 years." (PMID 32090076, 2020). "HBV co-infection, baseline CD4/CD8 ≥1, lower baseline HIV-RNA, and AEHI diagnosis in recent years (2012-2014) were independently associated with a shorter time to virological suppression." (PMID 32258852, 2020). "In conclusion, we found that factors including older age, female sex, black race, HCV coinfection, lower CD4 cell counts, VL ≥400 copies/ml, and lower eGFR were associated with an increased risk of anemia." (PMID 32197585, 2020). "Because co-infection with HCV induces higher CD4+ T cell activation in HIV patients, it would be expected that HIV-1 proviruses integrate into sites that are preferentially transcribed in HIV/HCV co-infected individuals, which would be worth analyzing." (PMID 32635221, 2020). "It is worth noting that four of five co-infections with CoSV in HIV-positive participants were detected in subjects with CD4+ T cell counts below 200 cells/μL (p = 0.02)." (PMID 32079128, 2020). "Pre-HAART CD4+ T-lymphocyte count and percentage are stronger predictors of immune recovery in TB-negative pediatric patients, suggesting that TB co-infection complicates the treatment of HIV in this cohort." (PMID 33059622, 2020). "Factors that were associated with incident anemia included: older age, female sex, black race, HCV coinfection, lower CD4 cell counts, VL ≥400 copies/ml and lower eGFR." (PMID 32197585, 2020). "Several studies have suggested an inverse correlation between CD4 T cell count and fibrosis in HBV-HIV co-infection, as well as an association between low baseline CD4 T cell counts and increased liver-related mortality." (PMID 31752729, 2019). "CD4+ T cells immunoreactivity increased in co-infection status when compared to BPIV-3 or BoHV-1 infections (p < 0.05)." (PMID 30823555, 2019). "In presence of a CM co-infection, there is CD4+ T cell depletion, high immune activation, and decreased cryptococcal memory cells." (PMID 31319498, 2019). "Several other factors have been involved on poor CD4 recovery upon successful cART such as older age, co-infection with HCV, high CD4+ T cell apoptosis, chronic immune activation, or poor thymic output." (PMID 30921390, 2019). "The long-term treatment outcome of visceral leishmaniasis (VL) patients with HIV co-infection is complicated by a high rate of relapse, especially when the CD4 count is low." (PMID 30789910, 2019). "Our objective was to evaluate the influence of HCV coinfection in HIV-1 viral reservoir size in resting (r) CD4+ T-cells (CD25-CD69-HLADR-)." (PMID 30944340, 2019). "In fact, it has been described that immune activation induced after co-infection with pathogens such as Mycobacterium tuberculosis enhances HIV-1 progression by increasing the number of activated CD4+ T cells." (PMID 30944340, 2019). "HIV co-infection was the main factor associated with mortality, however little is known when the HIV diagnosis was made, ARVs started and monitoring of changing CD4 counts and viral load while on treatment." (PMID 31295277, 2019). "HIV-HBV co-infection was associated with lower CD4+ T-cell count as well as higher HIV-1 viral load compared to both HIV mono- infection and HIV-HCV co- infection (p<0.05) respectively." (PMID 31002687, 2019).
co-infection (continued). "Age, duration of HIV diagnosis, ART use, current CD4 count, injection drug use, cigarette use, hepatitis B and C co-infection, province of residence, education, food security and income were associated with abnormal menstruation in bivariate analyses." (PMID 31881068, 2019). "Clinically relevant fibrosis at end of follow-up was predicted by HCV co-infection, lower baseline CD4 T cell counts and increased HIV RNA level at the end of study." (PMID 31752729, 2019). "The relative surge and decline in the expression of T cell surface markers outlines a variation in the differentiation of CD4+ T cells during ART treatment during CM co-infection." (PMID 31319498, 2019). "They had similar characteristics as compared with patients with a single episode (i.e., age, sex, CDC stage, frequency of HBV and HCV co-infection and of late presentation, CD4+ count and nadir at the time of the first BSI)." (PMID 30931978, 2019). "Various causes of immune activation have been unveiled, including residual viral production, coinfections, CD4 T-cell lymphopenia, immune senescence, metabolism disorders, CD4 T-cell subset deregulation, and microbial translocation." (PMID 31572392, 2019). "Future studies employing RNA sequencing of Mtb-specific CD4 T will be necessary to more comprehensively define CD4 T cell signatures of latent and active TB, and further define how co-infection with HIV impairs protective T cell immunity to Mtb infection." (PMID 31497018, 2019). "The prevalence and clinical correlates of HIV-HBV co-infection, namely reduced CD4 T cell count and fibrosis, reinforce the need for routine HBV screening among HIV-infected patients." (PMID 31752729, 2019). "Patients with low CD4 count are 3.5 times more likely to have TB/HIV co-infection as compared to high CD4 count (OR: 3.53, 95% CI: 1.55, 8.06)." (PMID 30281631, 2018). "Co-infection with HIV was common (57.2%) with significant immunosuppression – median CD4 was 173 (IQR 69–336)." (PMID 29581435, 2018). "SIV/SFV co-infection in that study was associated with higher SIV viral loads (VLs), lower CD4+ T-cell counts and lower survival." (PMID 30544924, 2018). "baumannii co-infection had a consistently low level of both CD4+ and CD8+ T-cell counts, while the survived H7N9-A." (PMID 30551738, 2018). "Interpretation of the CD4 cell count in individuals with HTLV-1/ATLL and HIV-1 co-infection: The CD4 cell count must be interpreted with caution in the HIV-1 positive individual with concurrent ATLL and or HTLV-1 co-infection." (PMID 30344845, 2018). "We analysed demographic data, co‐infections, clinical stage, CT and number of cycles, viral load, CD4 and CD8 lymphocytes (before, during and after CT), immune recovery at follow‐up and mortality." (PMID 29671462, 2018). "Concurrent Plasmodium and CHIKV co-infection inhibited migration of donor CD4+ T cells towards the joints of co-infected recipients by ~6-fold." (PMID 30254309, 2018). "Each biomarker was log transformed and entered into a univariate logistic regression model and a logistic model adjusted for HBV co-infection, HCV co-infection, race/ethnicity, age at last visit, education, smoking and CD4+ cell count." (PMID 33521162, 2018). "As immune regulation leading to suppressed joint swelling is dependent on the lymph node, expansion kinetics of CD4+ T cells in the pLN during concurrent co-infection was profiled." (PMID 30254309, 2018). "In this prospective, cross-sectional observational study 110 patients having TB-HIV co-infection were assessed for clinical presentation and correlation with CD4 count." (PMID 30915136, 2018). "In this study, we showed the prevalence of single and co-infection of Cryptosporidium, Cyclospora & Microsporidium with stratified CD4+ cells count." (PMID 30369995, 2018).